KCNE2 (potassium voltage-gated channel subfamily E regulatory subunit 2)
Diseases named in the same sentence as KCNE2 in open-access papers (continued):
Sharing a sentence is not in itself a finding about the gene and the disease.
myocardial infarction (3 papers, 2015 to 2024). Gross necrosis of the myocardium, as a result of interruption of the blood supply to the area, as in coronary thrombosis. "After the original report linking a SNP near the human KCNE2 locus to early-onset myocardial infarction (MI), a different SNP within the human KCNE2 gene itself was reported to be associated with predisposition to CAD, and related findings have followed." (PMID 33464998, 2021). "Reduced expression of KCNE2 has also been observed in heart failure following myocardial infarction." (PMID 39272981, 2024).
Ventricular arrhythmia (3 papers, 2019 to 2024). "However, the presence of the KCNE2 abnormality in mice undergoing RIPC processing results in reduced susceptibility to life-threatening ventricular arrhythmia." (PMID 39272981, 2024). "However, RIPC‐treated Kcne2‐/‐ mice were less susceptible to lethal ventricular arrhythmia." (PMID 30737904, 2019). "Here, we examine two different forms of remote ischemic preconditioning (limb and liver), and find that both were effective at preventing lethal ventricular arrhythmias in Kcne2‐/‐ mice." (PMID 30737904, 2019). "Given the complexity of SCD in the Kcne2‐/‐ mouse model and potential parallels to human SCD (KCNE2‐associated and otherwise), we sought to investigate potential treatment approaches focused on reducing the incidence of ischemia‐initiated ventricular arrhythmias." (PMID 30737904, 2019). "In the present study, we find a clear ability of RIPC (either limb or liver) to completely prevent SCD, and limit the incidence and severity of ventricular arrhythmias and AV block, in a mouse model of acquired LQTS, the Kcne2‐/‐ mouse line." (PMID 30737904, 2019).
Congenital Long QT Syndromes (2 papers, 2014 to 2022). "Point mutations in KCNE2 have been shown to cause Long QT Syndrome 6, a phenotype recapitulated in knockout mouse models of Kcne2." (PMID 25127743, 2014).
migraine (2 papers, 2011 to 2022). "A recent study of ion transport genes and migraine susceptibility provided evidence for a potential role of the potassium, voltage-gated, ion channel, KCNE2 gene on chromosome 21q22.11." (PMID 22030984, 2011). "Moreover, we found a genome-wide pleiotropy between lower levels of an accessory subunit of voltage-gated potassium channels, KCNE2, and migraine risk." (PMID 35546551, 2022).
ventricular tachycardia (2 papers, 2013 to 2019). A disorder characterized by an electrocardiographic finding of three or more consecutive complexes of ventricular origin with a rate greater than a certain threshold (100 or 120 beats per minute are commonly used). "KCNE2 c.161T>C has been related to exercise induced ventricular tachycardia, Torsade des Pointes ventricular tachycardia, diminished potassium flux, a less readily activation and a more rapid deactivation." (PMID 23936059, 2013).
acquired long QT syndrome (1 paper, 2019). A form of long QT syndrome in which malfunction of the cardiac ion channels is caused by drugs or metabolic abnormalities. "Mice lacking the Kcne2 gene, which encodes a potassium channel β subunit associated with acquired Long QT syndrome were exposed to IR injury via coronary ligation." (PMID 30737904, 2019).
Atrophy (1 paper, 2010). Any weakening or degeneration, especially through lack of use. "The appearance of SPEM in Kcne2−/− mice in the absence of either H. pylori or classic oxyntic atrophy suggests that the ‘functional atrophy’ caused by Kcne2 deletion may be enough to trigger SPEM." (PMID 20625512, 2010).
cardiac hypertrophy (1 paper, 2024). "The absence of KCNE2 led to an increase in serum angiotensin II and thus inactivation of GSK-3β to prevent cardiac hypertrophy." (PMID 39272981, 2024).
dilated cardiomyopathy (1 paper, 2024). Cardiomyopathy which is characterized by dilation and contractile dysfunction of the left and right ventricles. "A deficiency of KCNE2, whether cardiac-specific or systemic, leads to dilated cardiomyopathy (DCM) and advanced HF." (PMID 39272981, 2024). "Therefore, the lack of some elements of Cav1.2 control in mice with a specific absence of KCNE2 in the heart may play a role in the early fatal development of dilated cardiomyopathy and heart failure." (PMID 39272981, 2024).
epilepsy (1 paper, 2019). A brain disorder characterized by episodes of abnormally increased neuronal discharge resulting in transient episodes of sensory or motor neurological dysfunction, or psychic dysfunction. "The expression patterns of KCNE2 in cardiac and neuronal tissue resemble that of HCN channels and gene variants increase the susceptibility to several of the same cardiac and neuronal disorders linked to HCN such as epilepsy and cardiac arrhythmias." (PMID 31235733, 2019).
Gastric Metaplasia (1 paper, 2021). Intestinal metaplasia of the gastric mucosa is an intermediate precancerous gastric lesion in the gastric cancer cascade from chronic gastritis and atrophy to dysplasia and adenocarcinoma. "Germline Kcne2 disruption causes achlorhydria, gastric hyperplasia, gastritis cystica profunda, adenomatous polyps and gastric metaplasia." (PMID 33464998, 2021).
glioblastoma (1 paper, 2025). The most malignant astrocytic tumor (WHO grade IV). "Glioblastoma studies included E5 (KCNJ10, KCNN3), E21 (KCNAB2), E26 (KCNE2, KCNJ13), E27 (KCNE4, KCNMB2-AS1), E31 (KCNJ10), E50 (KCND3), and E51 (KCNIP1, KCNJ16, KCNN2)." (PMID 40867621, 2025).
heart failure (1 paper, 2024). Inability of the heart to pump blood at an adequate rate to meet tissue metabolic requirements. "Reduced KCNE2 plasma channel function is associated with ventricular tachyarrhythmias and Torsades de Pointe (TdP), one of the most important causes of death in patients with heart failure." (PMID 39272981, 2024).
melanoma (1 paper, 2020). A malignant, usually aggressive tumor composed of atypical, neoplastic melanocytes. "From a clinical perspective, knowledge on Kcne2 in the OPL might be important for a better understanding of the pathophysiology of (electronegative) retinal dystrophies or autoimmune phenomena such as melanoma-associated retinopathy." (PMID 32191288, 2020).
retinal dystrophies (1 paper, 2020). "Should future studies indeed reveal that Kcne2 mutations cause retinal dystrophy (or dysgenesis), patients diagnosed with LQT6 should routinely be seen by an ophthalmologist." (PMID 32191288, 2020).
cancer (5 papers, 2010 to 2021). A tumor composed of atypical neoplastic, often pleomorphic cells that invade other tissues. "Controlling the false discovery rate at 5%, ECAR selected six genes CHRM3, CTCFL, KCNE2, MLANA, MSMP, TTLL2, many of which have been reported to be associated with lung function or cancer." (PMID 34857823, 2021). "Several subunits are upregulated (e.g. Cavβ, Cavγ) and downregulated (e.g. Kvβ) in cancer, while other subunits have been functionally implicated as oncogenes (e.g. Navβ1, Cavα2δ1) and tumour suppressor genes (e.g. CLCA2, KCNE2, BKγ1) based on in vivo studies." (PMID 31071485, 2019). "Out of all the Kv auxiliary subunits however, KCNE2 has the most established link to cancer." (PMID 31071485, 2019). "Potassium channels have emerged as a potential target for anti-cancer therapies, including KCNQ1, hERG and Kv2.1, all of which are α subunit partners of KCNE2." (PMID 20625512, 2010).
tumour (5 papers, 2010 to 2024). "The hERG potassium channel α subunit, which forms complexes with the KCNE2 ancillary subunit in human heart, is over-expressed in some tumors, and has been identified as a tumor survival factor as has Kv2.1." (PMID 20625512, 2010). "Deficiency of either Kcne2 or Kcnq1 results in achlorhydia, gastric hyperplasia, and neoplasia, but the impact on iron absorption has not, to our knowledge, been investigated." (PMID 25127743, 2014). "The altered activity of mutant hERG appears to explain the increased malignancy of the tumours, and in STAD, reduced levels of the regulatory β-subunit KCNE2 lead to an increased hERG current." (PMID 36792990, 2023).
KCNE2 also shares sentences with these, for which no sentence is quoted: Arrhythmia (4 papers); hypothyroidism (3); Brugada syndrome (2); coronary artery disease (2); type 2 diabetes mellitus (2); Alzheimer disease (1); Anxiety (1); atrophic gastritis (1); AV block (1); behavioral disorders (1); cardiac arrest (1); catecholaminergic polymorphic ventricular tachycardia type 1 (1); cyst (1); depression (1); Down syndrome (1); dyslipidemia (1); gastric tumors (1); gingival overgrowth (1); iron deficiency (1); ischemia (1); liver (1); Long QT Syndrome 6 (1); nonalcoholic fatty liver disease (1); pituitary hormone deficiency (1); polymorphic ventricular tachycardia (1); retinopathy (1); Sinus bradycardia (1); sudden infant death syndrome (1); Torsade des Pointes (1); Turner syndrome (1).